VCAM1 (vascular cell adhesion molecule 1)
Diseases named in the same sentence as VCAM1 in open-access papers (continued):
Sharing a sentence is not in itself a finding about the gene and the disease.
Sepsis (continued). "Elevated serum level of VCAM1 was a more powerful predictor for septic encephalopathy in adult community‐onset sepsis on admission." (PMID 34825737, 2022). "The levels of VCAM1 (p = 0.010), B2M (p = 0.004), and ApoE (p = 0.039) were showing an increased tread in three groups, and B2M and ApoE were showing peak values in the sepsis group." (PMID 34825737, 2022). "Our results indicated that sepsis serum promoted the adhesion of leukocytes to HUVECs by improving the expression of VCAM-1 and ICAM-1." (PMID 35145983, 2022). "We found that the level of VCAM1 was showing an increased tread among non‐sepsis, sepsis, and septic shock groups, with a peak value in the sepsis group." (PMID 34825737, 2022). "The levels of VCAM1 (p = 0.010), B2M (p = 0.004), and ApoE (p = 0.039) were showing an increased tread in three groups, with the peak values of B2M and ApoE in the sepsis group." (PMID 34825737, 2022). "In this study, the combination of ApoC3, VCAM1, B2M, and ApoE proteins were screened and identified as biomarkers for sepsis by using iTRAQ‐2D‐LC‐MS/MS method." (PMID 34825737, 2022). "Follow-up in vivo study should be done to investigate the effect of RM on the expression of E-selectin and VCAM-1 in animal model of experimental sepsis." (PMID 36544136, 2022). "Leukocyte adhesion to the vasculature and expression of VCAM-1 and ICAM-1 are associated with the development of multiple organ failure in severe sepsis." (PMID 35145983, 2022). "Increased expression of ICAM-1 and VCAM-1 facilities the recruitment of macrophages and neutrophils into the myocardium, leading to inflammatory response in sepsis." (PMID 32411123, 2020). "Increased expression of adhesion molecules, such as ICAM-1 and VCAM-1, has been shown to recruit neutrophils and macrophages into the myocardium, leading to cardiac dysfunction in sepsis." (PMID 32411123, 2020). "Expression of IL6, ICAM1, and VCAM1 were significantly upregulated following treatment of the HMECs with LPS for 24 h confirming induction of sepsis." (PMID 31231228, 2019). "Based on that, we suggest, that VCAM-1 signaling appears to play a distinct role in CD34+/CD133+-stem cell homing in the course of sepsis." (PMID 29601599, 2018). "Our current work does not provide mechanistic insights into the proposed importance of VCAM-1 expression on CD34+/CD133+-stem cells for homing processes in sepsis." (PMID 29601599, 2018). "There is more positive staining of ICAM and VCAM-1 in the late-septic mice myocardium compared with sham control, and miR-155 mimic transfection attenuated sepsis-mediated expression of myocardial ICAM-1 and VCAM-1." (PMID 28525390, 2017). "The mRNA expression of ICAM-1 and VCAM-1 in liver and lung were remarkably elevated after burn sepsis." (PMID 26550025, 2015). "Although this study demonstrates that serum VCAM-1 level on presentation is a more powerful predictor of SE in severe sepsis patients than lactate concentration and other adhesion molecules on admission, this study has several limitations." (PMID 24883317, 2014). "Inflammatory mediators and cell adhesion molecules including ICAM-1, VCAM-1, P-selectin, and E-selectin participate in inflammatory sepsis induced lung injury." (PMID 25120287, 2014). "Second, VCAM-1 level on presentation is a more powerful predictor of SE in severe sepsis patients than lactate concentration and other adhesion molecules on admission by stepwise logistic regression and AUC analysis." (PMID 24883317, 2014). "It is for instance possible to reveal the impact of sepsis, acute hyperglycemia, acute ethanol intoxication, or aging on brain endothelium expression of VCAM-1 using MPIO-based molecular MRI in mice." (PMID 25505871, 2014). "Consistent with these published reports, our results show that sepsis is associated with elevated circulating levels of soluble ICAM-1, VCAM-1 and E-selectin." (PMID 20942957, 2010).
Sepsis (continued). "By inhibiting the expression of ICAM-1/VCAM-1 and suppressing the phosphorylation and internalization of VE-cadherin, 4-OI effectively reduces leukocyte adhesion and vascular leakage, which are critical factors in sepsis-induced organ injury." (PMID 40524158, 2025). "We thus hypothesized that the spatiotemporal expression of E-selectin and VCAM-1 proteins in pulmonary microvascular beds in sepsis would coincide with p65 and c-Jun pathway activation." (PMID 39200137, 2024). "Moreover, miR-126-5p and 3p in EPC-EXOs separately inhibit LPS-induced HMGB1 and vascular cell adhesion molecule 1 (VCAM1) levels in human microvascular ECs (HMVBCs), thereby improving sepsis in mice." (PMID 38840175, 2024). "Moreover, a review has confirmed that five different soluble adhesion molecules are associated with the presence of sepsis, specifically, E-selectin, L-selectin, P-selectin, ICAM-1, and VCAM-1." (PMID 38153527, 2024). "Similarly, our study showed that IFN-γ signaling pathway proteins (ACTG1, HSP90AB1, and VCAM1) were significantly higher in patients with HLH than in patients with sepsis." (PMID 37653176, 2023). "Furthermore, PKCδ inhibition was lung protective and decreased sepsis-induced VCAM-1 and ICAM-1 endothelial expression." (PMID 38259971, 2023). "Sepsis is associated with upregulation of endothelial cell adhesion molecules including ICAM-1 and VCAM-1, and this mechanism may also contribute to the accumulation of monocytes within plaques following pneumonia." (PMID 37033482, 2023). "The investigators hypothesized that VCAM1 reflected endothelium dysfunction, β2-microglobulin reflected sepsis-induced kidney, ApOC3 reflected hepatic secretory function, and ApoE reflected coagulation system failure." (PMID 36831207, 2023). "For example, during the cytokine-induced changes as observed in sepsis, IL-1β (which was part of the cytomix cocktail to stimulate the mouse ECs in our study) is released and adhesion molecules (such as VCAM-1 and SELP) are upregulated from human ECs during inflammation." (PMID 35955534, 2022). "However, the MMP8 inhibitor suppressed the leukocyte adhesion promoted by sepsis serum by decreasing the expression of VCAM-1, ICAM-1, p-p38, and p-ERK1/2." (PMID 35145983, 2022). "The increase in sepsis severity might reflect an increasing need for CD34+/CD133+-stem cell-based vascular regeneration facilitated by an improved homing via VCAM-1." (PMID 29601599, 2018). "Our data suggest, that VCAM-1 upregulation on CD34+/CD133+-stem cells could play a crucial role in their homing in the course of sepsis." (PMID 29601599, 2018). "VCAM-1 is an inducible endothelial cell adhesion molecule that is scarcely expressed in resting endothelium and highly upregulated upon inflammatory stimulation during hemorrhagic shock and sepsis." (PMID 29763440, 2018). "During sepsis, this imbalance could contribute to alteration of microvascular tone and integrity, as well as the activation of cell adhesion molecules, such as VCAM-1 and ICAM-1." (PMID 28333102, 2017). "P- and E-selectin, ICAM-1 and VCAM-1 all undergo proteolytic cleavage of the extracellular region of the membrane-bound receptor and levels of these soluble forms are increased in experimental and clinical sepsis." (PMID 20942957, 2010). "Cathepsin B (CatB), vascular cell adhesion protein 1 (VCAM-1), neutrophil gelatinase-associated lipocalin (NGAL), protein S100-A9, prosaposin, and thrombospondin-1 levels were significantly increased in the patients with sepsis compared with those of the controls (p < 0.001)." (PMID 39049003, 2024). "Interestingly, a previous study revealed VCAM1 overexpressed on endothelial cell-derived extracellular vesicles during sepsis, facilitating the activation of the NF-κB pathway by interacting with integrin subunit alpha 4 (ITGA4) on the monocyte surface thereby regulating monocyte differentiation." (PMID 38956604, 2024).
Sepsis (continued). "An index combining the levels of four proteins (β2-microglobulin >3.7 mg/L, VCAM1 >2216.8 ng/mL, ApoC3 ≤54.532 μg/mL, ApoE >62.45 mg/L) and two conventional infection biomarkers (procalcitonin, C-reactive protein yielded an AUC of 0.772 for sepsis identification." (PMID 36831207, 2023). "Lipopolysaccharide (LPS), a Gram-negative bacterial component, is an important sepsis-associated mediator that induces the expression of adhesion molecules such as E-selectin and VCAM-1 upon its binding to dedicated pattern recognition receptors on endothelial cells (EC)." (PMID 36544136, 2022). "Studies with more potent drugs encapsulated into anti-VCAM-1 SAINT-O-Somes will in the future reveal whether this delivery system can be further developed for efficacious endothelial directed delivery of drugs in the treatment of sepsis." (PMID 29763440, 2018). "ICAM-1, VCAM-1 and E-selectin are important cell adhesion factors that regulate the activity of inflammatory and vascular endothelial cells, pro- and anti-inflammatory factors, as well as inflammatory cell migration to tissues and organs; thus, these factors play an important role in sepsis." (PMID 25780398, 2015). "In sepsis, ECs become activated, leading to an increase in the expression of various adhesion molecules such as ICAM-1, VCAM-1, E-selectin, P-selectin, and vWF." (PMID 39974277, 2025). "The VCAM-1 mRNA fold change correlated well with the HDL-C level in the whole population (r = –0.563, p < 0.0001) and the sepsis group (r = –0.370, p = 0.0007)." (PMID 38603717, 2024). "Our findings indicate that SP upregulates the expression of ICAM1 and VCAM1 on vascular endothelial cells in the liver and lungs, thereby increasing leukocyte infiltration in these tissues of mice with CLP surgery-induced sepsis by activating NK1R." (PMID 38928206, 2024). "Dexamethasone-loaded anti-VCAM-1 SAINT-O-Somes specifically targeted VCAM-1-expressed endothelial cells and effectively reduced inflammation in the kidneys during sepsis." (PMID 38794195, 2024). "In mice with CLP-induced sepsis, immunofluorescence microscopy showed higher immunoreactivity of ICAM-1 and VCAM-1 that co-localized with structures identified by CD31 staining than in sham-operated control mice." (PMID 38254684, 2024). "In macrophages, the most differentially expressed genes after sepsis include S100a9, S100a8, Hbb-bs, Fth1, AW112010, Spic, Cxcl2, Cd14, Hmox1, and Vcam1." (PMID 38343542, 2024). "This study aimed to explore the effects of Kupffer cell inactivation on ICAM-1 and VCAM-1 expression in liver and lung endothelial cells in mice following CLP-induced sepsis." (PMID 38254684, 2024). "We also investigated the expression levels of ICAM-1 and VCAM-1 proteins in lung tissue and their immunoreactivity in structures localized with CD31 expression in GdCl3-pretreated mice with CLP-induced sepsis." (PMID 38254684, 2024). "CatB, VCAM-1, NGAL, S100-A9, prosaposin, and TSP-1 levels were significantly increased in the sepsis group (p < 0.001) compared with those of the controls." (PMID 39049003, 2024). "The study found that the expression of CD62L, VCAM-1 and CD62E was greater in patients with S-AKI when compared with patients with sepsis alone." (PMID 36333626, 2023). "qPCR and Western blotting demonstrated that the mRNA and protein levels of VCAM-1 and ICAM-1, induced by sepsis, were elevated, but this elevation was mitigated by echinacoside treatment." (PMID 38001778, 2023). "Effects of CLP-induced sepsis on ICAM-1 and VCAM-1 expression were less prominent at these early time points in these organs." (PMID 38020105, 2023). "Meta-analysis of biomarkers ICAM-1 (SMD 0.41; 95% CI 0.05–0.76; p = 0.03; I2 = 50%) and VCAM-1 (SMD 0.55; 95% CI 0.12–0.98; p = 0.01; I2 = 82%) revealed higher pooled mean concentration in patients with SAE compared to the patients with sepsis alone." (PMID 36802387, 2023).
Sepsis (continued). "VCAM-1 and ICAM-1 are markers of vascular endothelial damage in sepsis and can be used to monitor the development of organ dysfunction, such as kidney injury." (PMID 37779910, 2023). "VCAM-1, ICAM-1, and E-selectin were reportedly upregulated in an experimental sepsis model of human umbilical vein endothelial cells." (PMID 35620579, 2022). "Resistin was also reported to be associated with endothelial cell adhesion molecules, including intercellular adhesion molecule 1 (ICAM-1) and vascular cell adhesion molecule-1 (VCAM-1), in sepsis." (PMID 35784283, 2022). "Leukocyte adhesion and mRNA and protein expression of VCAM-1 and ICAM-1 were significantly increased in the sepsis serum group compared to that in the control group, as was the protein expression of p-p38 and p-ERK1/2." (PMID 35145983, 2022). "Our results were further validated in an in vivo model of sub-lethal LPS-induced sepsis, whereby siRNA mediated knockdown of UCA1 and HULC lncRNAs prevented induction of VCAM1, ICAM1, and IL6, as assayed by immunohistochemistry." (PMID 31231228, 2019). "In the case of septicemia, neutrophil granulocytes express α4ß1 (very late antigen 4, VLA-4) on their surface, acting as a ligand for VCAM-1 (vascular cellular adhesion molecule 1, CD106), which is upregulated in response to inflammatory mediators." (PMID 30657059, 2019). "Taken together, these results indicate that increase in proinflammatory ICAM1, VCAM1, and IL6 in HMECs during LPS induced sepsis in vitro is at least in part due to increase in expression of the lncRNAs HULC and UCA1." (PMID 31231228, 2019). "In the present study, significantly elevated expression levels of VCAM-1 and ICAM-1 were observed in the lung tissue of mice carrying HCN of DEFA1/DEFA3 at 24 h after sepsis onset compared with those of mice with LCN of DEFA1/DEFA3 and WT mice." (PMID 30718392, 2019). "The expression of VCAM-1, ICAM-1, E-selectin and L-selectin by CD34+/CD133+-stem cells was significantly upregulated in septic patients, and correlated with sepsis severity." (PMID 29601599, 2018). "Treatment with LPS, an important pathogenicity factor that lead to cardiac depression in experimental sepsis, significantly stimulated TNF-α and VCAM-1 expression in rat CMECs." (PMID 29615637, 2018). "We determined IFN-γ produced shortly after sepsis induction altered IFN-γR1 expression and function of vascular endothelium leading to impairments in VCAM-1 and CXCL9 expression upon exposure to exogenous or TRM-derived IFN-γ." (PMID 28910403, 2017). "In vivo transfection of miR-155 mimic, we found miR-155 attenuated late sepsis-mediated expression of myocardial ICAM-1 and VCAM-1." (PMID 28525390, 2017). "Similar findings of increased VCAM-1 and ICAM-1 levels have been observed in sepsis and correlate with prognosis in this condition." (PMID 27578545, 2016). "In the setting of sepsis, endothelial cells showed a marked increase in surface ICAM-1 and expression of VCAM-1 on endothelial cells." (PMID 25269519, 2014). "Expression of endothelial adhesion molecules such as E-selectin, VCAM-1, and ICAM-1, are a consistent feature of sepsis." (PMID 19416526, 2009). "The deletion of ETS1 in HUVEC effectively inhibited the upregulations of VCAM-1, E-selectin, PAI-1, and TF induced by LPS in both protein and mRNA levels, suggesting the regulatory importance of ETS1 in EC activation during sepsis." (PMID 40369168, 2025). "This assumption was supported for example by VCAM1 and ICAM1, which at day 1 showed the lowest levels in cluster 3 (regulation pattern α), and for which increasing plasma levels are well known to be related to sepsis severity." (PMID 40898225, 2025). "As a response, this also increases the expression of cell-adhesion molecules, such as intercellular adhesion molecule-1 (ICAM-1) and vascular cell adhesion molecule-1 (VCAM-1), where the levels of cell-adhesion molecules directly correlate with sepsis severity and organ dysfunction." (PMID 41374401, 2025).
Sepsis (continued). "The activity of myeloperoxidase and the concentration of ICAM1 and VCAM1 in the liver and lungs, as well as the expression of ICAM1 and VCAM1 on vascular endothelial cells in these tissues, increased in mice with CLP surgery-induced sepsis." (PMID 38928206, 2024). "The current study aimed to investigate the location of activated p65 and c-Jun pathways in EC, of expression of E-selectin and VCAM-1 as representatives of endothelially restricted adhesion molecules, and of leukocyte recruitment in mouse pulmonary microvascular beds in CLP-induced sepsis in time." (PMID 39200137, 2024). "During sepsis, immune cells interact with endothelial cells, inducing a pro-adhesive and pro-thrombotic phenotype rich of tissue factor (TF), E-selectin, ICAM-1, vascular cell adhesion molecule 1 (VCAM-1), and von Willebrand factor (vWF)." (PMID 38294676, 2024). "This study tested the hypothesis that Kupffer cells contribute to tissue injury in sepsis via the alteration of adhesion molecules (ICAM-1 and VCAM-1) present on the endothelial cells in liver and lung tissue." (PMID 38254684, 2024). "E-selectin protein was expressed in a subset of microvessels at 4 and 7 h after sepsis initiation, while VCAM-1 was expressed in a scattered pattern in alveolar tissue and microvessels, without discernible changes during sepsis development." (PMID 39200137, 2024). "The induction of sepsis resulted in increased expression of liver and lung ICAM-1 and VCAM-1." (PMID 38254684, 2024). "The anti-inflammatory function of GLP1-RAs was suggested to be through the inhibition of tumor necrosis factor alpha (TNFα) and decreases in vascular cell adhesion protein 1 (VCAM-1), intercellular adhesion molecules 1 (ICAM-1) and E-selectin expression in an animal sepsis model." (PMID 36932379, 2023). "The qPCR results showed that kaempferol inhibited significantly the mRNA level of ICAM-1 compared with saline-treated CLP group at 24 h, but there were no significant changes of MCP-1 and VCAM-1 in sepsis." (PMID 37440431, 2023). "In an in vitro experimental model of sepsis, there was progressive endothelial cell activation in correlation with the severity of sepsis, with significantly increased expression of surface adhesion receptors, such as ICAM-1, VCAM-1 and vWF, etc.." (PMID 37700349, 2023). "VCAM-1 (1.004 ± 0.06 vs. 4.508 ± 0.840, p < 0.05) and ICAM-1 (1.001 ± 0.04 vs. 3.552 ± 0.04, p < 0.05) mRNA expression was significantly increased in sepsis serum-treated HUVECs compared to the control group." (PMID 35145983, 2022). "Indeed, sepsis led to increased expression of ICAM-1, VCAM-1 and P-selectin in WT mice with reduced expression of these adhesion molecules in septic CTTN KO mice comparable to sham controls." (PMID 35625756, 2022). "We previously reported that elevation in endothelial biomarkers ANGPT2/ANGPT1 ratio, VCAM1, and vWF distinguished children with ARDS due to indirect (e.g., extrapulmonary sepsis or trauma, shock, transfusion, pancreatitis) compared to direct (e.g., pneumonia, aspiration, drowning) lung injury." (PMID 35913450, 2022). "An increase in sepsis severity resulted in both and increase in CD34+/CD133+-stem cells and VCAM-1-expression by those cells, which might reflect an increase in need for vascular repair." (PMID 29601599, 2018). "Our study now shows, that VCAM-1 expression is also increased specifically on CD34+/CD133+-stem cells during sepsis, which has not been investigated before." (PMID 29601599, 2018). "In emergency department patients with sepsis, resistin and NGAL correlated with the expression of the endothelial cell adhesion molecules (VCAM-1, ICAM-1) and were associated with septic shock, but not with mortality." (PMID 30517161, 2018). "In pulmonary microvessels of mice with CLP-sepsis, one reason why VCAM-1 protein expression is likely not involved in neutrophil and T lymphocyte accumulation could be related to the endothelial surface layer (ESL) composed of the glycocalyx." (PMID 39200137, 2024).